RIPK3 (receptor interacting serine/threonine kinase 3)
Diseases named in the same sentence as RIPK3 in open-access papers (continued):
Sharing a sentence is not in itself a finding about the gene and the disease.
retinal diseases (3 papers, 2017 to 2025). "In sharp contrast, both RIPK1 and RIPK3 proteins were detected within MCMV-infected of wildtype MAIDS-10 mice, as well as MCMV-infected eyes of MAIDS-10 mice deficient in either NLRP3, NLRP1b, or AIM2, all of which exhibited an atypical pattern of retinal disease." (PMID 41011779, 2025).
spinal cord injury (3 papers, 2018 to 2022). Penetrating and non-penetrating injuries to the spinal cord resulting from traumatic external forces (e.g., WOUNDS, GUNSHOT; WHIPLASH INJURIES; etc.). "Necroptosis, a regulated necrosis pathway mediated by the receptor-interacting protein kinases 1 and 3 (RIPK1 and RIPK3), is induced following spinal cord injury (SCI) and thought to contribute to neuronal and glial cell death." (PMID 29686269, 2018). "In spinal cord injury (SCI), lysosomal damage contributed to accumulation of RIPK3 proteins and followed necroptosis." (PMID 35402535, 2022).
squamous cell carcinoma (3 papers, 2020 to 2023). A carcinoma arising from squamous epithelial cells. "Differences in expression of RIPK1, RIPK3, and pMLKL were examined by comparing the immunoreactive score (IRS) in the groups of histological subtypes (squamous cell carcinoma, adenocarcinoma, adenosquamous carcinoma), grading (G1-G3), TNM- and FIGO-classification." (PMID 37197430, 2023). "Highly positive expression of CHIP showed a trend toward better OS (HR 0.531, 95% CI 0.244–1.154, p = 0.110) but not for that of RIPK3 in squamous cell carcinoma." (PMID 32521727, 2020). "CHIP(−)/RIPK3(+) showed a trend toward lower OS (HR 1.686, 95% CI 0.884–3.215, p = 0.113) but not for DFS in squamous cell carcinoma." (PMID 32521727, 2020).
autoimmune hepatitis (2 papers, 2021 to 2023). Hepatitis caused by autoantibodies. "Of concern, was the observation that in concanavalin A (ConA)-induced autoimmune hepatitis, RIPK3 deletion was protective, whereas RIPK1 inhibition exacerbated disease, accelerated animal death, and was associated with increased hepatocyte cell death." (PMID 34921136, 2021).
Autoimmunity (2 papers, 2016 to 2023). The occurrence of an immune reaction against the organism's own cells or tissues. "There is evidence to suggest that the transcriptional program activated downstream of RIPK3 is mainly responsible for driving the immunogenic role of necroptosis in environments ranging from infection to cancer transformation and autoimmunity." (PMID 37904220, 2023). "Necrotic cell death plays a significant role in the pathogenesis of autoimmunity and necrotic pathways mediated by PARP1 and RIPK3 are among the best characterized." (PMID 27669412, 2016).
B cell lymphoma (2 papers, 2018 to 2022). "SuDHL10 B-cell lymphoma cells have low or undetected levels of RIPK3 and MLKL." (PMID 29527209, 2018).
cervical squamous cell carcinoma (2 papers, 2015 to 2022). A squamous cell carcinoma arising from the cervical epithelium. "MLKL is a prognostic biomarker for cervical squamous cell carcinoma and has recently been identified as a key RIPK3 downstream component of TNF-induced necroptosis." (PMID 36685937, 2022). "Of note, our in situ analyses revealed heterogeneous RIPK3 expression patterns in cervical squamous cell carcinomas and adenocarcinomas." (PMID 25888634, 2015).
chronic lung disease (2 papers, 2020 to 2022). According to the definitions of the American and British Thoracic Societies, including pulmonary functional tests, X-rays, and CT scans for items such as fibrosis, bronchiectasis, bullae, emphysema, nodular or lymphomatous abnormalities. "Programmed necrosis (necroptosis) is a cellular program regulated by RIPK1 (receptor-interacting protein kinase 1) and RIPK3, and MLKL (mixed lineage kinase domain-like pseudokinase) in chronic lung diseases." (PMID 32357474, 2020).
congestive heart failure (2 papers, 2019 to 2025). Failure of the heart to pump a sufficient amount of blood to meet the needs of the body tissues, resulting in tissue congestion and edema. "As noted, the majority of PETROS patients had presentation RIPK3 levels below the limit of detection; only congestive heart failure and blunt trauma mechanism were associated with higher RIPK3 levels at this time point." (PMID 31253195, 2019).
corneal infection (2 papers, 2022). A viral or bacterial infectious process affecting the cornea. "Our unpublished observations using the HSV1 corneal infection model, higher viral titers were observed in RIPK3 kinase inactive mice, which is lack of RIPK3 kinase mediated necroptosis." (PMID 35464953, 2022).
Duchenne muscular dystrophy (2 papers, 2018 to 2025). Duchenne muscular dystrophy (DMD) is a neuromuscular disease characterized by rapidly progressive muscle weakness and wasting due to degeneration of skeletal, smooth and cardiac muscle. "In Duchenne muscular dystrophy (DMD), genetic ablation of Ripk3 in mdx mice significantly reduced myofibre degeneration, inflammation, and fibrosis, leading to improved muscle function, establishing RIPK3 as a key degenerative mediator." (PMID 41334559, 2025).
E. coli infection (2 papers, 2024 to 2025). "Concurrently, increased p-RIPK3 levels were also detected in pulmonary BALF cells after E. coli infection (including L929 cells treated with TNF-⍺ and Z-VAD as a positive control of p-RIPK3)." (PMID 40359428, 2025).
enteritis (2 papers, 2019 to 2022). Inflammation of the small intestine. "Previous studies have shown that caspase-8 could cleave RIPK3 to inhibit necroptosis of IECs during the process of enteritis caused by Salmonella, thereby playing a role in maintaining the intestinal barrier function and limiting the colonization of pathogens." (PMID 35110556, 2022).
Fabry disease (2 papers, 2021 to 2023). Fabry disease (FD) is a progressive, inherited, multisystemic lysosomal storage disease characterized by specific neurological, cutaneous, renal, cardiovascular, cochleo-vestibular and cerebrovascular manifestations. "We first showed the role of RIPK3 in the pathogenesis of Fabry disease." (PMID 33513913, 2021). "However, there has been no report on the association between RIPK3 and Fabry disease." (PMID 33513913, 2021). "Fifth, RIPK3 expression could not be confirmed in human tissue because we did not have human kidney samples of patients with Fabry disease." (PMID 33513913, 2021). "However, the role of RIPK3 was not elucidated in Fabry disease." (PMID 33513913, 2021).
glaucoma (2 papers, 2024 to 2025). Increased pressure in the eyeball due to obstruction of the outflow of aqueous humor. "Also, RIPK1/RIPK3 inhibition or RIPK1/3 gene manipulation can prevent RGC loss in several models of glaucoma, such as ischemia/reperfusion, optic nerve crush, and glutamate excitotoxicity." (PMID 40345829, 2025). "TNF is a potent inflammatory agent in the pathology of glaucoma, and TNF-related necroptosis is promoted by the RIPK1/RIPK3 axis." (PMID 40345829, 2025).
Glomerular sclerosis (2 papers, 2020 to 2025). Accumulation of scar tissue within the glomerulus. "However, RIPK3 gene knockout failed to reduce the glomerulosclerosis (supplementary result), that might explain the lack of effect in ACR by RIPK3 blockade." (PMID 32591618, 2020).
herpes simplex encephalitis (2 papers, 2022 to 2024). Herpes simplex virus encephalitis (HSE) is caused by the infection of the central nervous system by Herpes simplex virus (HSV) that could have a devastating clinical course and a potentially fatal outcome particularly with delay or lack of treatment. "We therefore performed studies to investigate possible mechanisms whereby RIPK3 might contribute to the neuropathogenesis of a fatal inflammation of the brain called herpes simplex encephalitis (HSE) caused by herpes simplex virus 1 (HSV1)." (PMID 36121858, 2022).
HIV-1 infection (2 papers, 2014 to 2015). The type species of lentivirus and the etiologic agent of acquired immunodeficiency syndrome (AIDS). "Further, because the specific combination of RIPK1 and RIPK3 lead to necroptosis and the nec-1 can inhibit their interaction, we have also performed RIPK1/RIPK3 co-IP to clarify that necroptosis occurs during HIV-1 infection." (PMID 24714696, 2014). "Whether HIV-1 infection leads to the formation of a RIPK1/RIPK3 complex that could promote NLRP3 inflammasome activation remains to be elucidated." (PMID 26297639, 2015).
idiopathic pulmonary fibrosis (2 papers, 2021 to 2023). Idiopathic pulmonary fibrosis (IPF) is a nonneoplastic pulmonary disease that is characterized by the formation of scar tissue within the lungs in the absence of any known cause. "In idiopathic pulmonary fibrosis (IPF) lungs, RIPK3 expression was elevated, apoptosis, and necroptosis were mostly seen in alveolar epithelial cells (AECs)." (PMID 37910384, 2023).
Insulin resistance (2 papers, 2016 to 2025). Increased resistance towards insulin, that is, diminished effectiveness of insulin in reducing blood glucose levels. "Together, these findings provide evidence that RIPK3 in WAT maintains tissue homeostasis and suppresses inflammation and adipocyte apoptosis, suggesting that systemic targeting of necroptosis might be associated with the risk of promoting insulin resistance in obese patients." (PMID 27323669, 2016).
intracerebral hemorrhage (2 papers, 2023). A cerebrovascular disorder characterized by bleeding into one or both cerebral hemispheres including the basal ganglia and the cerebral cortex. "Necroptosis induced by receptor‐interacting protein kinase 3 (RIPK3) is engaged in intracerebral hemorrhage (ICH) pathology." (PMID 37553782, 2023). "As one of the mechanisms of parthanatos, AIF showed the ability to interact with RIPK3 in the nucleus and induce necroptosis in intracerebral hemorrhage mice, and intervention with CsA blocked the RIPK3–AIF complex by inhibiting mPTP opening." (PMID 38026442, 2023). "Our previous study showed that RIPK3 induced AIF expression and its nuclear translocation after intracerebral hemorrhage injury." (PMID 37553782, 2023).
keloid (2 papers, 2022 to 2023). An irregularly shaped, elevated mark on the skin caused by deposits of excessive amounts of collagen during wound healing. "A bioinformatics analysis of the data showed that human keloid scar tissuecontains significantly more RIPK3+ fibroblasts compared to normal skin.RIPK3+Vim+ cells were found both in mouse wound bed and human keloid." (PMID 38234604, 2023). "A subpopulation of RIPK3+Vim+ cells was found inboth human keloid and a mouse wound, with the cell number being significantlygreater in the mouse wound bed compared to healthy skin." (PMID 38234604, 2023). "Compared with normal skin fibroblasts, there were more TUNEL staining-positive cells, higher RIPK1 and RIPK3 expressions as well as MLKL phosphorylation in keloid fibroblasts (P < 0.01), which were all reversed by NaHS pretreatment (P < 0.01)." (PMID 35774378, 2022).
lichen planus (2 papers, 2022 to 2025). A chronic, recurrent, pruritic inflammatory disorder of unknown etiology that affects the skin and mucus membranes. "Our findings demonstrate a statistically significant increase in the expression of IL-1β, IL-6, and RIPK3 in the skin biopsy samples of SJS/TEN patients compared to those of lichen planus (LP) patients and normal controls." (PMID 39941220, 2025). "Mixed supernatant of T cells derived from the lesions of lichen planus and lupus erythematosus induced phosphorylation of RIPK3 and MLKL in keratinocytes, but the inducing effect is dependent on the presence of TNF-α and IFN-γ in supernatant." (PMID 36344541, 2022). "Our findings highlight that IL-1β, IL-6, and RIPK3 play pivotal roles in these disease processes, with significantly elevated expression levels observed in the skin of SJS/TEN patients compared to those with lichen planus (LP) or normal controls." (PMID 39941220, 2025). "Our findings indicate that IL-1β, IL-6, and RIPK3 may play potential roles in the disease process, with significantly elevated expression levels in the skin of SJS/TEN patients compared to those with lichen planus (LP) or normal controls." (PMID 39941220, 2025).
liver failure (2 papers, 2021 to 2023). A liver disease characterized by the liver losing or has lost all of its function. "However, when comparing no organ failure and single organ failure, we observed that the elevated plasma RIPK3 levels were associated with single liver failure." (PMID 34921136, 2021). "Circulating RIPK3 and albumin levels may have the potential to reflect chronic hepatitis or liver failure prior to hospitalization, and further studies are needed to differentiate ALF from ACLF." (PMID 37640752, 2023). "RIPK3 were also higher in the presence of any type of organ failure apart from respiratory failure and more importantly increased in patients with single liver failure compared to no organ failure." (PMID 34921136, 2021).
lupus nephritis (2 papers, 2016 to 2025). Glomerulonephritis in the context of systemic lupus erythematosus. "The RIPK3 inhibitor, GSK ́872, which binds and inhibits catalytic activity of the kinase domain of RIPK3, has also shown protection in several mouse models, including acute lung injury and lupus nephritis." (PMID 39705008, 2025). "In contrast, in the kidney, the expression of genes involved in pyroptosis, e.g. NLRP3 and CASP1 were significantly increased and TNFR1, RIPK1, RIPK3, CIAP1/2 and GPX4 were significantly decreased along the progression of lupus nephritis (LN)." (PMID 27811014, 2016).
lymphopenia (2 papers, 2022 to 2023). Reduction in the number of lymphocytes. "Through TBK1‐IRF3 and RIPK3‐MLKL signaling, RPA1 deficiency initiated necroptotic cell death on recent thymic emigrants and proliferative T cells, consequently resulting in lymphopenia and increased susceptibility to autoimmune diseases." (PMID 36721037, 2023). "Consistently, lymphopenia was recapitulated in the Ripk3−/−Casp8ΔE385/ΔE385 and Mlkl−/−Casp8ΔE385/ΔE385 recipients characterized by CD8+ T cell deficiency in blood and decreased B cells, T cells, and their subsets in the spleen, bone marrow, and blood." (PMID 35064213, 2022). "Collectively, these results demonstrate that RIPK1 dosage-dependent and RIPK1 kinase-independent scaffold function contributes to lymphopenia and myeloid bias in Ripk3−/−Casp8ΔE385/ΔE385 mice." (PMID 35064213, 2022). "Consistently, myeloid bias and lymphopenia in the spleen and lymphopenia in the bone marrow were also significantly relieved in Ripk1+/−Ripk3−/−Casp8ΔE385/ΔE385 mice compared to those in Ripk3−/−Casp8ΔE385/ΔE385 mice." (PMID 35064213, 2022). "Collectively, caspase-8 cleavage together with RIPK3 or MLKL suppresses the intrinsic lymphopenia of hematopoietic stem cells." (PMID 35064213, 2022). "To determine whether T cell necroptosis is the main cause for the lymphopenia induced by RPA1 deficiency, we crossed the CKO mice (CD4creRpa1fl/fl) with Ripk3−/− mice and generated the CD4creRpa1fl/fl Ripk3−/− mice." (PMID 36721037, 2023). "Next, we asked whether lymphopenia was intrinsic to Ripk3−/−Casp8ΔE385/ΔE385 and Mlkl−/−Casp8ΔE385/ΔE385 hematopoietic stem cells (HSCs)." (PMID 35064213, 2022). "Importantly, the complete blood count results showed increased WBC and lymphocyte in the peripheral blood of Ripk1+/−Ripk3−/−Casp8ΔE385/ΔE385 mice compared to WT mice, suggesting that lymphopenia and myeloid bias in Ripk3−/−Casp8ΔE385/ΔE385 mice were largely alleviated by halving RIPK1 dosage." (PMID 35064213, 2022). "We demonstrated an unexpected role of caspase-8 auto-cleavage cooperating with RIPK3 or MLKL and RIPK1 in lymphopenia regulation." (PMID 35064213, 2022).
metastatic tumor (2 papers, 2016 to 2021). "Interestingly, RIPK3 expression was lower in metastatic tumors than in normal counterparts." (PMID 33996591, 2021). "Cells from the metastatic tumor 147L lacked RIPK3 expression, yet SM-164 sensitized these cells to TNFα as efficiently as cells from the RIPK3-expressing tumors 493L and 1029LV." (PMID 27129149, 2016).
muscular dystrophy (2 papers, 2022 to 2025). Muscular dystrophy (MD) refers to a group of more than 30 genetic diseases characterized by progressive weakness and degeneration of the skeletal muscles that control movement. "Muscular dystrophy patients and dystrophin-deficient mice displayed an upregulation of RIPK3 which indicates necroptosis activation." (PMID 35990890, 2022).
myonecrosis (2 papers, 2018 to 2022). "RIPK3 depletion represses the necrotic spike affecting mdx mice at 3 weeks of age, indicating that the TNFα-mediated myonecrosis at the onset of mdx pathogenesis is due to necroptosis." (PMID 36613804, 2022). "In dystrophin-deficient Golden retriever muscular dystrophy (GRMD) dogs, evidence of RIPK3-driven myonecrosis is also found in the diaphragm and the heart." (PMID 36613804, 2022). "In TAs of 2-week-old mdx mice (i.e., before the onset of myonecrosis), the levels of Ripk1, Ripk3, and Mlkl transcripts were similar to those in TAs from C57BL/10 controls." (PMID 30194302, 2018). "IgG uptake reduction in the mdxRipk3−/− myofibres was associated with a significant diminution of cell infiltrate, and a 40% decrease in macrophages, indicating that RIPK3 has a role in the inflammatory response to myonecrosis." (PMID 30194302, 2018). "In polymyositis, few myofibres are immunoreactive to antibodies directed against RIPK3 and MLKL, and myonecrosis is reduced in a mouse model for C protein-induced myositis depleted for MLKL and RIPK3." (PMID 36613804, 2022). "Interestingly, while two-thirds of myonecrosis affecting mdx hindlimb muscles at 3 postnatal weeks is driven by RIPK3, our results suggest no crucial involvement of RIPK3 at time points when the TA is undergoing less degeneration later in life." (PMID 30194302, 2018).
nephritis (2 papers, 2016 to 2018). Inflammation of renal tissue. "To determine whether RIPK3 is important in the final phase of the nephritis, i.e. the tissue damage induced by antibodies and complement, we investigated the role of RIPK3 in the development of nephritis induced by administration of NTS." (PMID 27669412, 2016). "We conclude that the necrosis, which develops during NTS-induced nephritis, is not due to RIPK3-driven pathway." (PMID 27669412, 2016). "We found that NTS-induced nephritis does not require the activation of RIPK3 pathway, neither in males, nor in females." (PMID 27669412, 2016). "The lack of protection from nephritis in the absence of RIPK3 in male or female mice led us to investigate the degree of necrosis in the kidneys of these mice during NTS-nephritis." (PMID 27669412, 2016). "Renal ischemia-reperfusion damage is in part mediated by RIPK3 and we have previously shown that absence of PARP1 reduced nephritis severity in male mice, but not females." (PMID 27669412, 2016). "In conclusion, our results demonstrate that RIPK3 is not critical for the development of nephritis not only in males but also in females, suggesting that the necrotic pathway in females is induced by an unknown mechanism, or by a redundant combination of PARP1 and RIPK3-driven pathways." (PMID 27669412, 2016).
osteoarthritis (2 papers, 2022 to 2025). A noninflammatory degenerative joint disease occurring chiefly in older persons, characterized by degeneration of the articular cartilage, hypertrophy of bone at the margins and changes in the synovial membrane. "Recently, through in silico binding assay and the CMap approach AZ-628, a potent RIPK3 antagonist was discovered, which seemed to modulate TRIM24-RIPK3 axis and targeted RIPK3-kinase activity, resulting in reduced osteoarthritis pathogenesis in the DMM mice model." (PMID 36361505, 2022).